FTO (FTO alpha-ketoglutarate dependent dioxygenase)
Diseases named in the same sentence as FTO in open-access papers (continued):
Sharing a sentence is not in itself a finding about the gene and the disease.
Obesity (continued). "This study aimed to investigate the effect of fat mass and obesity-associated (FTO) gene rs9939609 polymorphism on the association between CRC and different types of dietary fats." (PMID 37543622, 2023). "The Fat Mass and Obesity-associated (FTO) gene was the first gene to be associated with body fat, obesity and BMI." (PMID 37614712, 2023). "FTO is the first gene linked to human obesity; it regulates energy metabolism and food intake, leading to obesity in animals." (PMID 37835645, 2023). "A study conducted in the Turkish population found that the FTO rs1421085 variant was associated with the risk of obesity only in women." (PMID 36765298, 2023). "In this study, we performed RNA-seq on human abdominal SC derived adipocytes with FTO rs1421085 risk-free or obesity-risk genotypes, which were differentiated by applying three types of protocols: white, active, or inactive beige." (PMID 37416800, 2023). "These are distinct from the polymorphic intronic sequences of FTO associated with human obesity which have been found to regulate IRX3 expression in adipocytes and hypothalamic neurons." (PMID 37539037, 2023). "Trials that assessed interactions between the same FTO genetic variants and macronutrients, including total fat and protein intake on obesity, conflicted across different LMICs and populations." (PMID 37664850, 2023). "The relationship between obesity and the minor allele ‘A’ of the FTO single-nucleotide polymorphism (SNP) rs9939609 is well established among adults and children from diverse ethnic backgrounds, including Chileans." (PMID 36979984, 2023). "The FTO gene was one of the first identified loci correlating with obesity in genome-wide association studies." (PMID 36983642, 2023). "The fat mass and obesity-associated (FTO) gene, discovered during a GWAS in 2007, has a robust association with obesity and higher BMI." (PMID 36717943, 2023). "The identification of the fat mass and obesity-associated gene (FTO) marked a significant milestone as it became the first gene with substantial influence on an individual’s susceptibility to common polygenic obesity." (PMID 37710301, 2023). "The association between fat mass and obesity (FTO) gene polymorphisms and BCa is influenced by the status of ERs." (PMID 36729355, 2023). "pylori were examined, and modifying effect of FTO (the fat mass and obesity-associated protein) on CD44 was verified by MeRIP–qPCR." (PMID 36918410, 2023). "The FTO gene has been reported as an obesity-associated gene and is also considered a risk gene for osteoarthritis (OA)." (PMID 34812958, 2022). "Obesity risk was higher in inactive individuals homozygous to FTO rs9939609 compared to inactive individuals heterozygous to FTO rs9939609 (OR = 1.78, 95% CI 1.23–2.57; p = 0.002 and OR = 1.4, 95% CI 1–1.93; p = 0.04), respectively." (PMID 36235854, 2022). "Efforts of genetic studies to find the genes involved in the energy balance have led to detection of several obesity-related genes including the leptin, melanocortin-4 receptor (MC4R), and fat mass and obesity-associated (FTO)." (PMID 36440355, 2022). "SIA notably did not detect positive selection at GWAS loci in the TCF7L2 gene associated with type-2 diabetes, the ANKK1 gene implicated in addictive behaviors, and the FTO gene associated with obesity." (PMID 34888675, 2022). "Fat mass- and obesity-associated (FTO) protein is a m6A RNA demethylase that is strongly linked to obesity and is highly expressed in certain types of acute myeloid leukemia." (PMID 35515106, 2022). "In this study, we investigated obesity-related polymorphisms in FTO and ADRB2 genes as candidate genetic risk factors for excessive GWG in pregnant women with pregestational DM using traditional or DASH diets." (PMID 35268025, 2022). "Few studies demonstrated the association of the FTO polymorphism with dietary fiber intake and obesity." (PMID 36263301, 2022).
Obesity (continued). "Several genetic variants of the FTO, such as rs17817449, have also been shown to confer a very significant risk for obesity." (PMID 36530622, 2022). "A possible association was also reported between the fat mass and obesity‐associated (FTO) single‐nucleotide polymorphisms (SNPs) and BC." (PMID 36403211, 2022). "Nevertheless, the precise functional relation between wine consumption, FTO variants and obesity risk should be further studied." (PMID 36235854, 2022). "It is subsequently erased by the demethylases alkane hydroxylase homolog 5 (ALKBH5) and fat mass and obesity-associated protein (FTO)." (PMID 36120301, 2022). "The main gene associated with FM and obesity is FTO, which regulates neurological and hormonal pathways, as reported in both mice and humans, associated with appetite and body energy consumption." (PMID 35565885, 2022). "Reported interactions include those between FTO and physical activity in adults where physical activity attenuated the effects of the FTO effect allele on obesity from an odds ratio of 1.30 to 1.22 per effect allele." (PMID 35016652, 2022). "We have demonstrated that eighteen studied FTO common SNPs are significantly associated with obesity in the Israeli population." (PMID 36235854, 2022). "FTO is the first demethylase identified, first thought to be a gene associated with obesity, enriched in the brain, especially in neurons, and plays an important regulatory role in the central nervous system." (PMID 35846376, 2022). "FTO was originally found to be associated with obesity and is the first m6A demethylase to be discovered in vitro, in early 2011." (PMID 36578520, 2022). "PMD lead SNP rs11646715 is in the FTO gene at chromosome 16q12.2 which encodes an mRNA demethylase and is well-known for its association with fat mass and obesity." (PMID 35414113, 2022). "Genome-wide association studies have identified the alpha-ketoglutarate dependent dioxygenase gene (FTO) as the first susceptibility gene of obesity." (PMID 35757166, 2022). "FTO is the first obesity susceptibility gene identified by a genome-wide association study and showed that multiple single nucleotide polymorphisms (SNPs) of FTO gene were associated with obesity risk." (PMID 35528183, 2022). "Fat mass and obesity-associated (FTO) rs7185735 and melanocortin-4 receptor (MC4R) rs476828 variants were genotyped." (PMID 35845810, 2022). "In contrast, FTO was first identified as an obesity-related gene by genome-wide association analysis." (PMID 35395767, 2022). "Using GWAS, scientists identified significant SNPs in the first intron of FTO that were associated with obesity." (PMID 35409166, 2022). "Among them, a fat mass and obesity-associated (FTO) gene was reported to be highly dysregulated and largely contributed to obesity." (PMID 35923209, 2022). "Similar pleiotropy was observed for FTO obesity variants on the dynamics and lineage-specific expression of distal genes such as IRX3 and IRX5." (PMID 35659055, 2022). "For instance, the fat mass and obesity associated (FTO) gene increases adipose tissue, especially in the abdomen area, as well as hyperandrogenism tends to an increase in PCOS' incidence." (PMID 36522620, 2022). "FTO (fat mass and obesity associated) is a recently discovered gene related to obesity and expressed in various tissues of the human body, especially with high expression in the brain." (PMID 35528183, 2022). "Variants located within FTO, fat-mass and obesity-associated gene, have been associated with several obesity-related phenotypes using GWAS." (PMID 35377406, 2022). "Our study is to the best of our knowledge the first to provide evidence for a possible interaction between wine consumption and FTO risk predisposition to obesity." (PMID 36235854, 2022). "Trans-fatty acids have been suggested to increase body mass index and waist circumference by altering some SNPs (single nucleotide polymorphisms) of the FTO (fat mass and obesity-associated) gene." (PMID 36320895, 2022).
Obesity (continued). "Several studies highlighted the underlying molecular mechanisms by which FTO is associated with obesity, given its role as an m6A demethylase, by denoting target gene transcripts that are affected by this post-transcriptional modification." (PMID 35409166, 2022). "A LP diet supplemented with RML increased (P < 0.05) total m6A levels in the liver and muscle and were accompanied by decreased expression of fat mass and obesity-associated protein (FTO) and alkB homologue 5 (ALKBH5)." (PMID 35821163, 2022). "Genome-wide association (GWAS) studies have found that fat mass and obesity-associated (FTO) gene and its single nucleotide polymorphisms (SNPs) are associated with obesity." (PMID 35865314, 2022). "In 2007, three independent groups demonstrated that a cluster of polymorphisms in the FTO first intron was strongly related to body mass and composition parameters and predisposes to overweight and obesity in children, teenagers, and adults." (PMID 35627568, 2022). "FTO was widely studied as a fat mass and obesity-associated protein associated to metabolic disorders such as diabetes and obesity." (PMID 36518594, 2022). "Our results suggest a complex relationship between the FTO variant and rCBF in individuals with overweight and obesity, such that rCBF appears to be higher in T/T homozygotes compared to A carriers in some brain regions, but lower in others." (PMID 36072887, 2022). "This study highlighted a potential mechanism underlying the obesity-prone eating behavior observed in FTO rs9939609 individuals." (PMID 35409166, 2022). "FTO was originally reported to be associated with weight gain and obesity in humans, and studies have shown that it regulates lipid metabolism in an m6A-dependent manner." (PMID 35568876, 2022). "This complexity became more evident when genome-wide association studies (GWAS) began to detect more genetic variants associated with obesity, such as those in fat mass and obesity-associated (FTO) or melanocortin 4 receptor (MC4R) genes, among many others." (PMID 36289722, 2022). "This is exemplified by the recent dissection of the regulatory landscape of the FTO locus, which has been strongly associated with the risk of obesity." (PMID 35205324, 2022). "FTO, a well-known gene associated with obesity, has been identified as a major genetic contributor to polygenic obesity in a cohort study of European populations." (PMID 35999587, 2022). "The human RNA demethylase FTO (fat mass and obesity associated) induces transcriptional activation in plants, suggesting a role for m6A in transcription." (PMID 36460653, 2022). "Obesity risk for inactive FTO rs9939609 homozygous men was significantly higher compared to inactive homozygous women (OR = 3, 95% CI 1.2–7.52; p = 0.019 and OR = 1.58, 95% CI 1.05–2.38; p = 0.03, respectively)." (PMID 36235854, 2022). "Fat Mass and Obesity-Associated (FTO) is the first susceptibility gene for obesity identified by the Gene-Wide Association Studies (GWAS)." (PMID 36530622, 2022). "FTO is also the first obesity susceptibility gene identified in the genome-wide association studies." (PMID 35528183, 2022). "Since the initial classification of FTO as an m6A demethylase, various studies started to unravel a connection between FTO’s demethylase activity and the susceptibility to obesity on the molecular level." (PMID 35409166, 2022). "The FTO (the fat mass and obesity-associated gene) has the greatest influence on BMI values of all known genes." (PMID 36142109, 2022). "The FTO gene is located on chromosome 16q12.2, and it has been implicated in determining not only obesity, but also other symptoms of the metabolic syndrome." (PMID 35625981, 2022). "The FTO gene is related to fat content and obesity in humans, and the FTO gene in pigs is linked to muscle development and the rate of lean meat." (PMID 36360207, 2022).
Obesity (continued). "Like ALKBH5, the primary function of FTO appears to be oxidation of m6A in mRNA, although FTO, the overexpression of which is closely linked to obesity and diabetes, also oxidizes the methyl groups of 3‐methylthymine (m3T) and 3‐methyluracil (m3U) in ssDNA." (PMID 35852137, 2022). "Obesity risk was significantly higher among FTO rs9939609 risk-allele carriers that were physically inactive as compared to non-risk inactive counterparts, both in the dominant, recessive and codominant models." (PMID 36235854, 2022). "FTO became notable in genome-wide association studies because single nucleotide polymorphisms located in its genomic locus are associated with obesity." (PMID 35422475, 2022). "Fat mass and obesity (FTO) associated gene is expressed in adipocytes and hypothalamus which encodes FTO protein (alpha-ketoglutarate dependent dioxygenase)." (PMID 35388304, 2022). "A more recent clinical study further corroborated the obesity-related polymorphisms in the FTO gene with increased susceptibility to osteoporotic bone fractures." (PMID 35883424, 2022). "Manifold studies showed that the strongest association of the FTO gene with overweight and obesity involved mainly A and G risk alleles of the following two SNPs: rs9930609 and rs9930506." (PMID 35806402, 2022). "The present study conducted secondary data analysis from a behavioral weight loss clinical trial to examine the relationship between the FTO rs9939609 and rCBF in adults with overweight or obesity." (PMID 36072887, 2022). "In an independent genome-wide association study, FTO dysfunction was shown to be a high-risk factor leading to early onset and severe obesity in European and Indonesian participants." (PMID 35406663, 2022). "Consuming SSBs significantly interacted with FTO rs8050136, rs1421085, rs9939609 and rs1121980 in risk-allele carriers to effect obesity (p = 0.013, p = 0.015 p = 0.049 and p = 0.017), respectively." (PMID 36235854, 2022). "It was suggested that FTO SNPs’ predisposition to obesity is race-specific, as the relationships between rs9939609 and obesity is inconsistent." (PMID 36235854, 2022). "Previous studies of the interaction of FTO common SNPs with lifestyle factors, focusing mainly on rs9939609, found that obesity predisposition due to FTO SNPs can be modified by physical activity, attenuating increase in BMI." (PMID 36235854, 2022). "A significant association affecting the repeated MetS score is seen in five SNPs of the fat mass and obesity associated (FTO) gene on chromosomal region 16q12., the strongest of which was with the variant rs80540136." (PMID 35054972, 2022). "Building upon the known association between the FTO genotype and BMI, one group of researchers employed a Mendelian randomization approach to explore the association between longitudinal obesity and common mental disorders, including depression." (PMID 35308733, 2022). "Association between the FTO (Fat mass and obesity-associated) genetic variant rs1421085 and severe obesity, for example, was higher using a comparison of homozygous genotypes than the additive model." (PMID 36314028, 2022). "The FTO gene, encoding a 2-oxoglutarate-dependent nucleic acid demethylase, has been demonstrated in related studies to be an obesity-associated gene." (PMID 35846376, 2022). "Genetically, TAL1 rs2984618 and a mutation in the CART gene were found to be associated with both obesity and depression, along with the relationship being partially mediated by some FTO variants." (PMID 35308733, 2022). "Human genome studies indicate a strong association between human fat mass and obesity-associated (FTO) gene variants and BMI in different populations." (PMID 35883424, 2022). "This in turn suggests that the association between obesity and depression is at least partially moderated by certain FTO variants." (PMID 35308733, 2022).
Obesity (continued). "On the other hand, rare forms of obesity that are uniquely due to defects of genes encoding for, e.g., FTO, melanocortin 4 receptor or leptin, have also been identified." (PMID 35741001, 2022). "Their studies confirm that variants in multiple enhancers within FTO obesity-associated regions regulate the expression of multiple genes (IRX3 and IRX5) in at least two obesity-relevant tissues (adipose and brain)." (PMID 35205324, 2022). "The single nucleotide polymorphism (SNP) rs9939609 in the fat mass and obesity associated fat mass and obesity associated gene (FTO) gene has been linked with increased BMI in adults." (PMID 36072887, 2022). "Following LPS administration, mice showed increases in m6A-RNA methylation in the myocardium with a corresponding decrease in the expression of Fat mass and obesity-associated protein (FTO, an m6A eraser/demethylase)." (PMID 34581943, 2022). "It has been reported that FTO is an obesity-associated protein with the role of catalyzing m6A demethylation." (PMID 35053496, 2022). "The fat mass and obesity associated (FTO) gene is an important factor related to hyperlipidemia and occurrence of cardiovascular diseases." (PMID 36185685, 2022). "Previously, a large amount of studies have covered that FTO contributes to the risk of obesity due to the population-based studies and the relevant experiments elaborating specific mechanisms." (PMID 35391794, 2022). "There is a formidable body of evidence supporting FTO gene’s association with both obesity and PCOS." (PMID 35679284, 2022). "Further analysis of the associated molecular mechanism revealed that DHA enhanced expression of the fat mass and obesity-associated gene (FTO), leading to reduced m6A levels of DNA damage-induced transcript 4 (Ddit4)." (PMID 35135551, 2022). "FTO alpha-ketoglutarate dependent dioxygenase (FTO, which is called fat mass and obesity associated in Mus musculus) gene was firstly identified for development-regulatory function." (PMID 33826123, 2022). "Different results were noted regarding FTO, which is considered the main gene associated with obesity." (PMID 36142109, 2022). "FTO originally considered as a susceptible gene plays an important role in lipid metabolism and accumulation and obesity." (PMID 35311620, 2022). "GWAS represent a powerful tool in establishing connections between FTO variants and phenotypical features of obesity such as BMI and waist circumference." (PMID 35409166, 2022). "GWAS analyses have identified multiple single nucleotide polymorphisms (SNPs) of the fat mass and obesity associated (FTO) genes." (PMID 37990728, 2022). "It is not clearly understood if the presence of specific FTO SNPs will increase the risk of obesity in patients receiving antipsychotic medications." (PMID 36362270, 2022). "Specifically, the single nucleotide polymorphism (SNP) rs9939609 in the FTO gene–a thymine (T) to adenine (A) substitution–increases obesity risk." (PMID 36072887, 2022). "Our review aims to confirm m6A demethylation as a risk factor in obesity and provoke new research in FTO and human disorders." (PMID 35409166, 2022). "The FTO gene, which encodes 2-oxoglutarate-dependent nucleic acid demethylase, has been reported as an obesity-associated gene and is expressed in many tissues, including the cerebral cortex, hypothalamus, pituitary, and muscle." (PMID 34812958, 2022). "A single base pair variation within the first intronic sequence of FTO proteins is associated with obesity in individuals." (PMID 35388304, 2022). "A notable example of a distally acting enhancer variant > 50 kb, is the obesity FTO locus variant rs1421085 regulating IRX3 and IRX5, which are 500 kb and 1,163 kb away respectively." (PMID 35365203, 2022). "Over 50% of the variance in BMI is heritable, and a common variation in the fat mass and obesity associated gene (FTO) accounts for most inter-person variance in body weight." (PMID 36072887, 2022).